CDK10 (cyclin dependent kinase 10)
Description:
Cyclin-dependent kinase that phosphorylates the transcription factor ETS2 (in vitro) and positively controls its proteasomal degradation (in cells). Involved in the regulation of actin cytoskeleton organization through the phosphorylation of actin dynamics regulators such as PKN2. Is a negative regulator of ciliogenesis through phosphorylation of PKN2 and promotion of RhoA signaling.
Synonyms: PISSLRE; ALSAS
Tractability: Small molecule: a drug acting on it is in phase 2 or 3 trials; a high-quality ligand is known; it belongs to a druggable protein family. PROTAC: it is named in the literature on targeted protein degradation; ubiquitination databases record sites on it; a small molecule that binds it is known.
Target class: Enzyme
Chemical probes: THAL-SNS-032 (high quality)
Gene: Protein-coding gene on chromosome 16 (89,680,737 to 89,696,369, forward strand). Ensembl gene ENSG00000185324.
Subcellular location: Cytoplasm, cytoskeleton, cilium basal body
Gene Ontology:
Molecular function: protein binding; protein serine/threonine kinase activity; cyclin-dependent protein serine/threonine kinase activity; ATP binding; cyclin-dependent protein kinase activity; protein kinase activity; protein serine kinase activity
Biological process: negative regulation of cilium assembly; peptidyl-threonine phosphorylation; regulation of actin cytoskeleton organization; G2/M transition of mitotic cell cycle; negative regulation of cell population proliferation; traversing start control point of mitotic cell cycle; regulation of mitotic cell cycle
Cellular component: ciliary basal body; nucleus
Genetic constraint (gnomAD): Loss-of-function variants: 55 observed, 51.24 expected, observed/expected ratio (o/e) 1.07, 90% interval 0.86 to 1.34. The synonymous counts are far from expectation, so gnomAD's model fits this gene poorly and the ratio says little. Missense variants: 589 observed, 476.46 expected, observed/expected ratio (o/e) 1.24, 90% interval 1.15 to 1.32. Synonymous variants: 255 observed, 198.76 expected, observed/expected ratio (o/e) 1.28, 90% interval 1.16 to 1.42.
Homologues: Orthologues: guinea pig CDK10 (97% identical), mouse Cdk10 (97% identical), rat Cdk10 (97% identical), pig CDK10 (94% identical), macaque CDK10 (86% identical), tropical clawed frog cdk10 (84% identical), dog CDK10 (82% identical), zebrafish cdk10 (81% identical), Drosophila melanogaster Cdc2rk (62% identical). Paralogues in human: CDK11B (49% identical), CDK11A (49% identical), CDK17 (39% identical), CDK12 (39% identical), CDK18 (38% identical), CDK7 (38% identical), CDK3 (37% identical), CDK13 (37% identical), CDK16 (37% identical), CDK14 (36% identical), CDK5 (36% identical), CDK2 (36% identical), and 14 more.
Diseases named in the same sentence as CDK10 in open-access papers:
CDK10 is named in the same sentence as 44 diseases in open-access papers, as found by Europe PMC text mining. Sharing a sentence is not in itself a finding about the gene and the disease. The quoted sentences say what the papers report.
breast carcinoma (15 papers, 2009 to 2025). "Lower level of CDK10 was associated with resistance to endocrine therapy in breast cancer patients." (PMID 38410280, 2024). "Importantly, CDK10 expression was associated with better overall survival and may be a predictor of prognosis in breast cancer." (PMID 34277407, 2021). "Cdk10 itself can be regulated in breast cancer cell lines by proteasomal degradation, which is promoted by phosphorylation at Thr133 through a yet unidentified kinase." (PMID 35291876, 2022). "The tumour suppressive role of Cdk10 in breast cancer was substantiated by a recent study which found that the Cdk10 gene was deleted in 80% of the cases in a Swedish breast cancer cohort." (PMID 35291876, 2022). "Cdk10 has tumour suppressive functions in many cancer types, including breast cancer, gastric carcinoma, liver cancer and glioma, but can also act as an oncogene in colorectal cancer." (PMID 35291876, 2022). "CDK10 was identified as a determinant of endocrine therapy resistance in breast cancer, with early recurrence being observed on tamoxifen-treated ERα-positive breast cancer patients with low CDK10 expression levels." (PMID 33686962, 2021). "This study used gene silencing to identify CDK10 as a modulator of tamoxifen resistance in breast cancer through regulation of p42/p44 MAPK pathway." (PMID 34277407, 2021). "The tumor-suppressor characteristics of cyclin-dependent kinase 10 (CDK10) have been demonstrated in nasopharyngeal carcinoma and breast cancer." (PMID 34830815, 2021). "Anticipating a mechanism similar to endocrine therapy resistance in breast cancer, CDK10 expression was shown to downregulate c-Raf levels in BTC." (PMID 34277407, 2021). "There is significant evident identifying CDK10 as an important modulator of tamoxifen sensitivity in breast cancer, suggesting a potential role for CDK10 in chemosensitivity in other cancers." (PMID 34277407, 2021). "Promoter hypermethylation was found to be a mechanism of CDK10 suppression in breast cancer and nasopharyngeal carcinoma." (PMID 34277407, 2021). "This study observed a significant inverse correlation between Pin1 and CDK10 expression in tamoxifen-resistant breast cancer." (PMID 34277407, 2021). "Although discovered in the pre-genomic era, CDK10 attracted little attention until it was identified as a major determinant of resistance to endocrine therapy for breast cancer." (PMID 28178678, 2017). "The clinical significance of the involvement of CDK10 in the response of MCF7 breast cancer cells to tamoxifen was investigated by measuring CDK10 expression levels in tumors from breast cancer patients subjected to an endocrine therapy." (PMID 28178678, 2017). "The expression of C1orf63 and CDK10, one known cell cycle-dependent tumor suppressor in breast cancer, was assessed by immunohistochemistry." (PMID 26209438, 2015). "CDK10 has been shown to play a role in cellular progression as well as a known prognostic factor predicting better outcome for breast cancers." (PMID 26209438, 2015). "Given the suggested role of C1orf63 on cell cycle exit, and its capability to predict better prognosis for breast cancers, we thus examined the relationship between C1orf63 and CDK10." (PMID 26209438, 2015). "Recent studies have shown that CDK10 is a potential tumor suppressor in breast cancers, and CDK10/Ets2/c-RAF signaling has been demonstrated as an important determinant of breast cancer resistance to endocrine therapy." (PMID 26209438, 2015). "We supposed that c-RAF was regulated by CDK10 in BTC in the same manner as described for breast cancer." (PMID 22209942, 2012). "Given that c-RAF has been identified as a target protein regulated by CDK10 and influences resistance to endocrine therapy for breast cancer, c-RAF was also examined." (PMID 22209942, 2012). "A previous study has reported that CDK10 expression is reduced in breast cancer and CDK10 silencing induces resistance to endocrine therapy." (PMID 22209942, 2012).
breast carcinoma (continued). "Research showed that the expression of CDK10 was over-expression in lung adenocarcinoma follicular lymphoma and seminomas, and low-expression in breast cancer patients who have poorer prognosis after surgical procedure." (PMID 22298115, 2012). "The results confirmed that the expression of c-RAF is regulated by CDK10 in BTC cells similarly to breast cancer cells." (PMID 22209942, 2012). "The reason why CDK10 is downregulated in breast cancer with aberrant DNA methylation is still controversial, CDK10 is being investigated as a tumor suppressor." (PMID 22209942, 2012). "Recent studies have shown that CDK10 is a potential tumor suppressor not only in breast cancer, but also in other tumors, such as seminoma." (PMID 22209942, 2012). "CDK10 is significantly downregulated in breast cancer compared to normal breast tissue." (PMID 34277407, 2021). "Given the tumor suppressive nature of CDK10 in breast cancer, HCC, BTC and gastric cancer, targeting CDK10 via pan-CDK inhibitors may have limited the therapeutic response." (PMID 34277407, 2021). "An inverse correlation between the expression of CDK10 and the degree of tamoxifen resistance suggests CDK10 could be an important determinant of tamoxifen resistance in breast cancer." (PMID 32296699, 2020). "Although discovered in the pre-genomic era, and at a time when the study of CDKs yielded major breakthroughs in the understanding of cell cycle regulation, CDK10 received little interest until it was identified as a major determinant of resistance to endocrine therapy for breast cancer." (PMID 28178678, 2017). "In an effort to identify determinants of resistance to endocrine therapy for breast cancer, a siRNA screen against the whole human kinome revealed CDK10 as a target whose silencing allowed cultured MCF7 breast cancer cells to grow efficiently in the presence of tamoxifen." (PMID 28178678, 2017). "We firstly took advantage of four publicly available microarray datasets, each including a cohort of patients with breast cancer, to evaluate whether mRNA expression of C1orf63 could be related to that of CDK10." (PMID 26209438, 2015). "This signaling pathway is regulated by CDK10 in breast cancer." (PMID 22209942, 2012). "Given that CDK10 has been identified as an important determinant of resistance to endocrine therapy for breast cancer, we decided to examine whether CDK10 influenced resistance of BTC cells to chemotherapy." (PMID 22209942, 2012). "In addition, the CDK10/Ets2/c-RAF signaling has been demonstrated as an important determinant of resistance to endocrine therapy for breast cancer." (PMID 22209942, 2012). "Initial reports have indicated that CDK10 may act as a tumor suppressor in breast cancer." (PMID 34277407, 2021). "Notably, patients with breast cancer whose tumours expressed low concentrations of CDK10 were shown to relapse much earlier than those with high CDK10 expression, suggesting that CDK10 may serve as a biomarker." (PMID 19126568, 2009). "The increase in ETS-2 protein upon low Cdk10 expression levels results in increased MAPK signalling and activation of the Raf/Ras pathway, which has been shown to confer tamoxifen resistance in breast cancer." (PMID 35291876, 2022). "Many identified targets of miR-210 such as suppressor anaphase-promoting complex, cyclin-dependent kinase 10, SERTA Domain Containing 2 are involved in cell cycle regulation and correlate with aggressiveness of breast cancer." (PMID 34299605, 2021). "The results revealed that the mRNA expression of CDK7, CDK8, CDK9, CDK10, CDK12, CDK19, and CDK20 was upregulated in patients with breast cancer." (PMID 33686962, 2021). "Among those CDKs, the expression levels of CDK10 and CDK19 were significantly higher in breast cancer than in normal breast tissues in Oncomine and the HPA datasets." (PMID 33686962, 2021). "CDK7, CDK10, and CDK11 were moderately expressed in normal breast tissues and highly expressed in breast cancer tissues." (PMID 33686962, 2021).
breast carcinoma (continued). "Then the relationship between C1orf63 and cyclin-dependent kinase 10 (CDK10), a known cell cycle-dependent tumor suppressor in breast cancer was investigated." (PMID 26209438, 2015). "Cyclin-dependent kinase 10 (CDK10) is a member of the Cdc2 family of kinases, and has been demonstrated to be an important determinant of resistance to endocrine therapy for breast cancer." (PMID 22209942, 2012). "Coincidentally, in MCF-7 breast cancer cells, it has been reported that there is a significant decrease in the number of G1 phase cells, in the absence of tamoxifen treatment, because of CDK10 silencing." (PMID 22209942, 2012). "For example, CDK10 mRNA and/or protein levels were found downregulated in biliary tract carcinomas, hepatocellular carcinomas, low-grade and, to a lesser extent, high-grade glial tumors and breast cancer tissues compared to adjacent noncancerous tissues." (PMID 28178678, 2017).
melanoma (6 papers, 2011 to 2024). A malignant, usually aggressive tumor composed of atypical, neoplastic melanocytes. "Despite this, further work is needed to determine if DNA methylation at cg00001687 is involved in the association between CDK10 expression and melanoma and the precise mechanisms underlying this link." (PMID 39137780, 2024). "We also found that the expression of ASIP and CDK10 was associated with hair colour, melanoma and basal cell carcinoma." (PMID 33248005, 2021). "For instance, random gene set number 81 contains the gene CDK10, which is found in a region of genome-wide significance in melanoma association studies." (PMID 22216283, 2011). "Furthermore, CDK10 has been identified to play a role in cell cycle regulation and is located in a locus (16q24) harboring SNPs associated with melanoma risk." (PMID 23133393, 2012). "In this study, the finding of up-regulation of CDK10 expression in vitiligo support the evidence that patients with vitiligo have a reduced risk of overall internal malignancies, melanoma, and non-melanoma skin cancer." (PMID 33679896, 2021). "In addition, ASIP gene expression was associated with self‐reported and diagnosed malignant melanoma, and BCC in both skin tissues, and CDK10 was associated with self‐reported and diagnosed malignant melanoma, and BCC in unexposed skin." (PMID 33248005, 2021). "used summary-based Mendelian randomization to show that CDK10 expression is reduced in self-diagnosed melanoma and in sun-exposed skin (compared to non-sun-exposed skin) via a pleiotropic effect with rs1805008, reinforcing our findings." (PMID 39137780, 2024).
STAR syndrome (6 papers, 2017 to 2025). "PRK2 has recently been linked to a newly established ciliopathy, STAR syndrome, where loss of Cdk10/ClnM activity in humans results in developmental abnormalities such as toe syndactyly, telecanthus, and anogenital and renal malformations." (PMID 32127582, 2020). "Since the majority of the other allelic variants consist of large deletions or splice site mutations likely to prevent cyclin M expression, it can be concluded that the CDK10/CycM protein kinase is deficient in STAR syndrome." (PMID 32762766, 2020). "Regardless, two C-terminal truncated forms of Cyclin M corresponding to the hypothetical translation products of two mutated genes identified in STAR syndrome patients were unable to bind to CDK10 in two-hybrid interaction assays." (PMID 28178678, 2017). "Conversely, another study showed that one 11-year old female patient with globally similar symptoms, but also with abnormal primary cilia, which is observed in STAR syndrome patients with cyclin M loss-of-function mutations or in the experimental CDK10/cyclin M knockdown." (PMID 33805800, 2021). "The binding of CDK10 to cyclin M is independent of the kinase domain, however, the interaction of CDK10 with cyclin M was shown to regulate the kinase activity of CDK10, in STAR syndrome." (PMID 34277407, 2021). "In most cases, these massive deletions prevent cyclin M expression, which leads to the conclusion that the heterodimer of CDK10/cyclin M is impaired in STAR syndrome." (PMID 33805800, 2021). "Since suppression of either cyclin M or CDK10 promotes ciliogenesis, it can be argued that Star syndrome can be classified as another type of ciliopathy." (PMID 33805800, 2021). "The recent study showing that CDK10/CycM represses ciliogenesis brings another important contribution to the understanding of the etiology of STAR syndrome." (PMID 28178678, 2017). "The fact that STAR syndrome presents features that are frequently observed in ciliopathies, such as renal, retinal and digital anomalies, prompted the exploration of a putative role of CDK10/CycM in ciliogenesis." (PMID 32762766, 2020). "Without STAR syndrome, the role of CDK10/CycM in ciliogenesis would probably be still unknown, especially if one considers that CDK10 was not retained among the hits of a sub-genome-scale RNAi screening that identified a number of novel modulators of ciliogenesis and cilium length." (PMID 32762766, 2020). "Hence, the combination of enhanced ETS2 levels and ciliary defects resulting from compromised CDK10/CycM activity may explain most, if not all, of the clinical features of STAR syndrome." (PMID 28178678, 2017).
colorectal cancer (5 papers, 2019 to 2024). A primary or metastatic malignant neoplasm that affects the colon or rectum. "A study on CDK10’s role in colorectal cancer revealed that it enhances cell growth, reduces chemosensitivity, and inhibits apoptosis by increasing the expression of BCL-2." (PMID 38609844, 2024). "Cdk10 is mostly described as a negative regulator of tumour growth, but one study reports positive effects of Cdk10 downregulation in colorectal cancer cell lines." (PMID 35291876, 2022). "The modulation of CDK10 expression in colorectal cancer indicates that CDK10 is involved in cell growth and it is associated with a reduction in chemosensitivity." (PMID 31354629, 2019). "CDK10 is highly represented in colorectal cancer where it takes part in the suppression of apoptosis and in the stimulation of tumor growth in vitro and in vivo." (PMID 31354629, 2019). "CDK10 has been identified as a candidate tumor suppressor in hepatocellular carcinoma, biliary tract cancers, and gastric cancer, but as a candidate oncogene in colorectal cancer (CRC)." (PMID 38609844, 2024). "CDK10 has been identified as both a candidate tumor suppressor in hepatocellular carcinoma, biliary tract cancers and gastric cancer, and a candidate oncogene in colorectal cancer (CRC)." (PMID 34277407, 2021). "Additionally, CDK10 has been shown to promote tumorigenesis in colorectal cancer (CRC)." (PMID 34277407, 2021). "CDK10 promotes cell growth, reduces chemosensitivity, and inhibits apoptosis by increasing the expression of BCL-2 in colorectal cancer." (PMID 38609844, 2024). "In the present study, CDK12 overexpression was associated with higher survival rate, while patients with downregulated expression of CDK10 and 16 exhibited lower OS, suggesting that CDK10/16 and CDK12 can be used as prognostic biomarkers for colorectal cancer patients." (PMID 35814446, 2022).
biliary tract cancer (4 papers, 2012 to 2021). "To investigate the expression and possible function of CDK10 in biliary tract cancer (BTC), we systematically examined CDK10 in tissues and cell lines." (PMID 22209942, 2012). "These functions are at least partially mediated via a negative regulation of c-RAF, thus offering a potential therapeutic approach for treatment of biliary tract cancer with low expression of CDK10." (PMID 22209942, 2012). "CDK10 restoration inhibits tumor growth, cell migration and survivability, and induces malignant cells to become sensitive to chemotherapy in the biliary tract cancer." (PMID 22209942, 2012). "In conclusion, we report that expression of CDK10 is downregulated in biliary tract cancer and that it functions as a tumor suppressor." (PMID 22209942, 2012). "Our results indicate that CDK10 plays a crucial role in the growth and survivability of biliary tract cancer, and offers a potential therapeutic target for this fatal disease." (PMID 22209942, 2012). "CDK10 has been identified as a candidate tumor suppressor in hepatobiliary cancers, including hepatocellular carcinoma (HCC) and biliary tract cancers (BTC)." (PMID 34277407, 2021).